STAT5A (signal transducer and activator of transcription 5A)
Diseases named in the same sentence as STAT5A in open-access papers (continued):
Sharing a sentence is not in itself a finding about the gene and the disease.
breast cancer (continued). "So far, very little attention has been given to a potential synergism between STAT5a and estrogen signaling, especially in the context of DCIS formation and progression, and which might also explain differing roles of STAT5a in breast cancer." (PMID 32633727, 2020). "Similarly, STAT5A represses BCL6 expression at the transcriptional level in breast cancer cell lines." (PMID 29728695, 2018). "The data therefore suggest that phospho-JNK and/or phospho-STAT5A/B levels may be used as predictors for HER-TKI sensitivity of breast cancer cells." (PMID 26735495, 2016). "We analysed STAT5A gene expression in breast cancer using the Oncomine database." (PMID 27014737, 2016). "•We show that in different independent studies STAT5A is downregulated in breast cancer." (PMID 27014737, 2016). "Examples of such nodes in our present study are STAT3, STAT5A and myosin light chains, whose validity was supported by in silico survival curve analysis and immunohistochemical examinations of their usefulness as prognosis markers of breast cancer." (PMID 26479444, 2015). "We have not examined the contribution of STAT5B in our study, although it has been suggested that the balance between STAT5A and B expression may be important in breast cancer progression." (PMID 24913037, 2014). "Indeed, others have shown that levels of the JAK2 phosphatase, PTP1B, are inversely correlated with nuclear levels of phosphorylated STAT5A and B in human breast cancer and that PTP1B suppressed the levels of PRL-induced phosphorylated STAT5A." (PMID 24913037, 2014). "Furthermore, prolactin-suppression of the Bcl6 oncogene in human breast cancer cell lines was preferentially mediated by Stat5a over Stat5b." (PMID 23036105, 2012). "Stat5a and Stat5b protein levels were quantified in situ in breast-cancer progression material." (PMID 23036105, 2012). "Current data support the concept of dual roles of Stat5a/b proteins as promoters of mammary tumorigenesis, and as suppressors of the progression of established breast cancer, although our knowledge of individual roles of Stat5a and Stat5b in breast cancer remains rudimentary." (PMID 23036105, 2012). "Low transcript levels for Stat5a but not Stat5b in breast cancer specimens were associated with poor clinical outcome." (PMID 23036105, 2012). "Levels of Nuc-Stat5a were markedly reduced during breast cancer progression, with significant loss of Nuc-Stat5a expression in IDC (P < 0.001) and greatest loss in lymph node metastases (P < 0.001)." (PMID 23036105, 2012). "The changes seen in this study in the reciprocal STAT5a/PRLR relationship with breast carcinoma may be due to signaling defects in this pathway." (PMID 21655368, 2008). "STAT5b is more abundantly expressed than STAT5a in prostate cancer and breast cancer cell lines." (PMID 17997837, 2007). "STAT5B has been implicated in migration, whereas loss of STAT5A was associated with disease progression, highlighting the importance in future studies to distinguish between the two STAT5 proteins to enrich clinical efficacy of STAT5 as a biomarker for breast cancer." (PMID 40507264, 2025). "During mammary cell growth, prolactin suppresses BCL6 expression through a STAT5A-related mechanism, suggesting that loss of prolactin-STAT5A signaling and concomitant increases of BCL6 may constitute a regulatory switch and facilitate undifferentiated histology and poor prognosis of breast cancer." (PMID 38124049, 2023). "Interestingly, the expression of STAT5A is similar to Notch3 levels in breast cancer cell lines." (PMID 38124049, 2023). "Influorescence staining revealed the expression and distribution of F-actin was regulated by STAT5A, while colony formation assay, wound healing and transwell assays predicted the inhibitory role of STAT5A in the colony formation, migratory and invasive abilities in breast cancer cells." (PMID 38124049, 2023).
breast cancer (continued). "In wound healing assays, STAT5A overexpression suppressed cell migration compared to the control group (p < 0.001), and in transwell assays, overexpression of STAT5A also suppressed both the migration and invasion of breast cancer cells compared with the control group." (PMID 38124049, 2023). "Therefore, we speculated that low expression of SOCS2 may promote breast cancer progression through regulation of STAT5A." (PMID 34120621, 2021). "Rather, pharmacologic inhibition or total knockdown of STAT5a had been the focus of previous work to understand STAT5a transcriptional functions, ignoring the gradation of STAT5a transcriptional function that may be in play in breast cancer and other pathologies." (PMID 34188118, 2021). "However, the role of STAT5a in the development of breast cancer is controversial." (PMID 34336684, 2021). "Targeting STAT5a might be a promising strategy for treating doxorubicin-resistant breast cancer." (PMID 34336684, 2021). "Therefore, phosphorylation of S780 may contribute to the potential for breast cancer cells to establish viable colonies, indicating a delicate balance for STAT5a regulation." (PMID 34188118, 2021). "Furthermore, it appears that paying closer attention to the subtype of estrogen receptor(s) expressed by the cells when STAT5a is present might also be of importance in fully predicting breast cancer cell behaviors." (PMID 32633727, 2020). "On activation by ligand NRG, it can activate the anti-proliferative JAK2-STAT5A pathway which results in activation, dimerization and nuclear localization of the transcription factor STAT5A which promotes transcription of genes mediating differentiation in particular breast cancer cell lines." (PMID 31092187, 2019). "In addition, we found that high mRNA expression STAT5a and STAT5b is significantly associated with RFS in breast cancer patients, implying that STAT5 may be an important promising biomarker for breast cancer." (PMID 29326301, 2018). "Given that system xc- is intricately involved in redox homeostasis, we previously examined whether representative STAT family members regulate xCT expression, demonstrating by ChIP analysis that STAT3 and STAT5A are able to directly bind to the xCT promoter in MDA-MB-231 human breast cancer cells." (PMID 27513743, 2016). "Furthermore, the mechanisms underpinning loss of Nuc-pYStat5a/b in breast cancer remain to be identified, and it is unknown whether reduced Nuc-pYStat5a/b levels in breast cancer may in part reflect reduced levels of Stat5a and/or Stat5b protein expression." (PMID 23036105, 2012). "Importantly, a recent study investigating the effects of STAT5a on breast cancer cell migration and invasion showed that prolactin (Prl)-induced activation of STAT5a inhibited migration and invasion of BT-20 and T-47D human breast cancer cells." (PMID 19630967, 2009). "Therefore, STAT5b is necessary for optimal migration of highly aggressive breast cancer cells, whereas expression of STAT5a is not required and cannot compensate for loss of STAT5b." (PMID 19630967, 2009). "This suggests that both STAT5A and STAT5B promote cyclin D1 expression in breast cancer through interacting with different cofactors." (PMID 40507264, 2025). "Conversely, knockdown of STAT5A expression with siRNA decreased the levels of E-cadherin, an epithelial marker, in MCF-7 breast cancer cells." (PMID 38124049, 2023). "In our preliminary experiments, the consistent expression pattern of STAT5A and Notch3 in different breast cancer cell lines was found and a CSL-binding site was predicted in the promoter region of STAT5A." (PMID 38124049, 2023). "TCGA datasets were used to evaluate the expression of STAT5A in normal and different cancerous tissues through TIMER2.0, indicating that STAT5A level was decreased in breast cancer tissues compared with normal ones." (PMID 38124049, 2023).
breast cancer (continued). "Impaired intracellular STAT3, STAT5A and STAT5B signaling has been reported in various solid tumors such as prostate, colon, glioma, head and neck tumors, melanoma, hemoblastosis and breast cancer." (PMID 36765714, 2023). "Namely, Ser81 phosphorylation by CK2 results in increased expression of STAT5A and WNT1 and thus plays a role in breast cancer cell biology also possibly affecting the process of inflammation related to breast cancer development and progression." (PMID 34638264, 2021). "We found that STAT5a- or ABCB1-expressing patients exhibited a significantly lower pCR rate, implying the vital roles of STAT5a and ABCB1 in chemoresistance in breast cancer." (PMID 34336684, 2021). "In order to investigate the relationship of NMI and STAT5A protein expression with breast cancer progression, we immunostained normal breast tissues and breast cancer tissues for NMI and STAT5A." (PMID 34078871, 2021). "Our results indicate that STAT5A, together with NMI protein expression in primary breast cancer tumors, is reduced compared to adjacent normal breast tissue." (PMID 34078871, 2021). "Then, we confirmed the essential roles of STAT5a and ABCB1 in doxorubicin resistance in breast cancer cells and the regulation of ABCB1 transcription by STAT5a." (PMID 34336684, 2021). "We performed immunohistochemical (IHC) staining of a breast cancer tissue microarray (TMA) using phospho-specific antibodies for pY694-, pS726-, and pS780-STAT5a, as well as total STAT5a." (PMID 34188118, 2021). "The roles of STAT5a and ABCB1 in chemoresistance in breast cancer and their regulation were further confirmed by IHC analysis of breast cancer tissues from 67 patients who received DOX-containing neoadjuvant treatment." (PMID 34336684, 2021). "Recently, suramin has been shown to interfere with intracellular signalling proteins in the WNT pathway to inhibit the growth of breast cancer cells in a mouse xenograft model, and to target SH2 domains of STAT5a/b and STAT1." (PMID 31409229, 2019). "During normal mammary gland development, STAT5A plays the more dominant role, whereas both STAT5A and STAT5B have been described as contributing to breast cancer pathophysiology." (PMID 27472371, 2016). "Inactivation of Stat5a in transgenic mice expressing transforming growth factor (TGF) α or the SV40 T antigen delayed hyperplasia and mammary cancer progression." (PMID 19450255, 2009). "Other transcription factors with indirect effects in breast cancer were E2F1 and STAT5A, which are essential in the regulation of tumor growth and apoptosis." (PMID 18358079, 2008). "The genetic interaction STAT5A → PPARA was among those selected, as in the case of the Dutch breast cancer data set." (PMID 18358079, 2008). "Previous studies have demonstrated that STAT5a and STAT5b are tyrosine phosphorylated by the EGFR and c-Src kinases, two kinases that are involved in breast cancer." (PMID 17997837, 2007). "Although STAT5A and STAT5B are often grouped together as STAT5, it is important to note that some differences between the two have been shown in normal mammary gland and breast cancer." (PMID 40507264, 2025). "As Notch3 and STAT5A perform similar tumor-suppressive effects on EMT and metastasis of breast cancer, current study investigated the relationship between STAT5A and Notch3 and their roles in tumorigenesis and metastasis of breast cancer." (PMID 38124049, 2023). "In addition, JAK2 and STAT5A overexpression cooperatively reverses EMT and promotes differentiation in human breast cancer cells, which explains the suppression of invasion of prolactin-activated STAT5A in mammary cancer cells." (PMID 38124049, 2023). "The STAT family was proposed as a biomarker or immune checkpoint inhibitor for prognosis prediction or therapy in various types of solid tumors, including STAT3 and STAT5A in breast cancer; STAT3, STAT5A, and STAT6 in lung cancer; and STAT3 and STAT5A in prostate cancer." (PMID 35646925, 2022).
breast cancer (continued). "In our study, pimozide inhibited STAT5a and ABCB1 in a dose-dependent manner and sensitized breast cancer cells to DOX, which could be rescued by overexpression of STAT5a or ABCB1." (PMID 34336684, 2021). "Statistical analysis suggested that patients with STAT5a-positive breast cancer had a lower pCR rate than STAT5a-negative patients." (PMID 34336684, 2021). "To investigate whether STAT5a can regulate the sensitivity of breast cancer cells to DOX, we knocked down and overexpressed STAT5a via siRNA and a plasmid in MCF7/DOX and MCF7 cells, respectively." (PMID 34336684, 2021). "STAT2, STAT4, STAT5a, STAT5b, and STAT6 had significantly favorable effect on RFS of breast cancer patients, but STAT1 had significant worse effect on RFS; STAT5b had significant favorable effect on PPS, while, STAT2 had significant worse effect on PPS for breast cancer patients." (PMID 29326301, 2018). "We have recently reported that Stat5a but not Stat5b expression was lost during progression of human breast cancer, and in cultured MCF-7 cells there was only a limited overlap in transcripts modulated by the two PRL-activated transcription factors." (PMID 23758962, 2013). "Most analyses of Stat5 in breast cancer specimens to date have focused on detecting either Stat5a or Stat5b or investigated Stat5 without discriminating between Stat5a and Stat5b." (PMID 23036105, 2012). "Protein levels of Stat5a but not Stat5b were reduced in primary breast cancer and lymph node metastases compared with normal epithelia." (PMID 23036105, 2012). "We chose to use the MDA-MB-231 breast cancer cell line because they are highly migratory and express both STAT5a and STAT5b proteins, whereas BT-549 breast cancer cells express only STAT5b (data not shown)." (PMID 19630967, 2009). "We and others found that STAT5b is the predominant STAT5a/b protein expressed in breast cancer cell lines and tissues, and that STAT5b, not STAT5a, mediates proliferation of breast cancer cells." (PMID 19630967, 2009). "Recent evidence indicates that STAT5b, but not STAT5a, has a proproliferative role in breast cancer, head and neck cancer, and prostate cancer." (PMID 17997837, 2007). "However, the relationship and potential regulatory mechanism between Notch3 and STAT5A was not verified in HER2-positive subtype of breast cancer." (PMID 38124049, 2023). "Transgenic overexpression of STAT5A leads to mammary carcinomas in the absence of other oncogenes." (PMID 35784527, 2022). "Pimozide, an FDA-approved psychotropic drug, inactivated STAT5a and downregulated the expression of ABCB1, thus sensitizing MCF7/DOX cells to DOX in vitro and in vivo, providing a promising strategy for treating patients with chemoresistant breast cancer in the clinic." (PMID 34336684, 2021). "Based on four independent clinical materials, reduced levels of nuclear-localized Stat5a were prognostic of unfavorable breast cancer outcome in patients who did not receive systemic adjuvant therapy and were associated with elevated risk of failure of antiestrogen therapy in patients." (PMID 23036105, 2012). "However, in those studies, STAT5a was overexpressed in the moderately migratory BT-20 and T-47D breast cancer cell lines, which contain little to no endogenous STAT5a." (PMID 19630967, 2009). "Since our previous studies demonstrated that STAT5b, but not STAT5a, elicits a proproliferative effect in breast cancer cells, and other studies have shown that Brk also increases proliferation of breast cancer cells, we focused our efforts on Brk-mediated activation of STAT5b." (PMID 17997837, 2007). "In addition, previous studies indicated that STAT5 activation is correlated with favorable breast cancer-specific and disease-free survival in lymph node-negative breast cancer, and that STAT5a plays a tumor suppressive role in cancers, including breast cancer." (PMID 37369132, 2023).
breast cancer (continued). "The constitutive, wide-ranging expression of pS780 suggests that it could result from a non-specific phosphorylation event in breast cancer pathogenesis, however studies performed herein determined that it has a non-redundant role for STAT5a in MCF7 breast cancer characteristics." (PMID 34188118, 2021). "However, the opposite pattern was seen in breast carcinomas lacking STAT5a expression." (PMID 21655368, 2008). "Specifically, METTL3 association with the CCND1 (cyclin D1) promoter region was reduced with STAT5B knockdown, but not STAT5A, which impaired cell cycle progression in hormone receptor-positive MCF7 breast cancer cells." (PMID 40507264, 2025). "The results suggested that the STAT5a/ABCB1 pathway was at least one, if not the main, mechanism by which pimozide functions in drug-resistant breast cancer." (PMID 34336684, 2021). "Thus, silencing of JNK and STAT5A/B appears to be involved in the anticancer effects of the HER-TKIs and inactivation of these signal effector molecules could therefore potentially serve as biological indicator for sensitivity of breast cancer cells against HER-TKIs." (PMID 26735495, 2016). "Stat5b but not Stat5a promoted in vitro migration of ER-negative BT549 and MDA-MB-231 breast cancer cells." (PMID 23036105, 2012). "Knockdown of STAT5b, but not STAT5a, inhibited migration of BT-549 and MDA-MB-231 breast cancer cells to serum by 60% to 80%, and inhibited migration equally over a range of serum concentrations (0.1% to 10% serum)." (PMID 19630967, 2009).